PPARA (peroxisome proliferator activated receptor alpha)
Diseases named in the same sentence as PPARA in open-access papers (continued):
Sharing a sentence is not in itself a finding about the gene and the disease.
Hepatic steatosis (continued). "The downregulation of circRNA_0046367 signified the loss of inhibition of miR-34a/PPARα interaction and led to lipid peroxidative damage, thereby reducing hepatic steatosis." (PMID 30191143, 2018). "Our data showed that MHY553 can bind to and activate PPARα, contributing to the amelioration of hepatic steatosis and inflammation associated with aging." (PMID 28545035, 2017). "circRNA_0046367/miR-34a/PPARα regulatory system represents a novel epigenetic mechanism underlying hepatic steatosis and related oxidative stress." (PMID 29018509, 2017). "The lipid droplet-associated proteins FSP27/CIDEC and LSDP5, regulated directly by PPARγ and PPARα, are associated with hepatic steatosis and insulin sensitivity." (PMID 26770990, 2016). "In fact, PPARα activation is associated with reduced hepatic steatosis through the regulation of a wide variety of genes involved in peroxisomal, mitochondrial, and microsomal fatty acid β-oxidation systems in the liver." (PMID 26539534, 2015). "PPARA is a transcription factor that has been implicated in hepatic steatosis and hepatic metabolic homeostasis through regulation of the hepatocyte nuclear factor-4 alpha (HNF4A) gene." (PMID 26206264, 2015). "Conversely, ineffective PPARα sensing or decreased fatty acid oxidation causes a reduction in energy burning that results in hepatic steatosis and steatohepatitis (especially during overnight or prolonged fasting)." (PMID 24524207, 2014). "This study also shows that ERC intake can ameliorate the hepatic steatosis that is associated with an increased expression of hepatic DNA binding activity of PPARα." (PMID 24444255, 2014). "Hepatic PPARα associated with the attenuation of insulin signaling and hepatic steatosis was upregulated by 2.35 fold in HFD rats." (PMID 24638096, 2014). "Treatment with a PPARα agonist decreased hepatic steatosis in mice on a methionine- and choline-deficient (MCD) diet." (PMID 22675337, 2012). "HCV infections areassociated with reduced hepatic PPARα expression, and PPARα is implicated inHCV core protein-mediated hepatic steatosis and dysregulated lipid metabolism." (PMID 19107217, 2008). "Additionally, LXR also activates PPARα, which regulates fatty acid oxidation and lipid metabolism, thus potentially reducing the risk of hepatic steatosis." (PMID 40926269, 2025). "Hepatic PPARα-deficient mice have aggravated liver steatosis and inflammation, with hyperlipidemia." (PMID 40564141, 2025). "Although the combination of Fgf15 overexpression and PPARα activation had an excellent effect on promoting weight loss and reducing hepatic steatosis, the dual treatments led to increased liver injury and expression of genes in inflammation, fibrosis, and antioxidation." (PMID 40815899, 2025). "Decreased PPARα expression leads to hepatic lipid accumulation, whereas PPARα activation increases the expression of fatty acid oxidation-related genes and reduces the risk of hepatic steatosis." (PMID 40487402, 2025). "This relationship prompted us to further investigate whether the PPARα/SIRT1-AMPK pathway was involved in miR-34a-regulated hepatic steatosis and its associated pathology." (PMID 41223206, 2025). "Furthermore, in addition to the reduced lifespan observed in PPARα knockout mice, it has been noted that liver-specific PPARα-deficient mice develop fatty liver disease as they age, even on a standard diet." (PMID 40507037, 2025). "Indeed, our results indicated that USP25 impaired the K48-linked ubiquitination and degradation of PPARα and that resupplying PPARα in USP25-deficient mice ameliorated diet-induced hepatic steatosis." (PMID 39395794, 2024). "Parallel to this, SIRT1 suppression in the mouse liver is sufficient to cause hepatic steatosis, an effect that may be mediated via Ppar-γ and Pparα, the key regulators of glycolysis and lipolysis." (PMID 37190114, 2023). "The loss of PPARα decreased fatty acid β-oxidation and aggravated hepatic steatosis in mice." (PMID 35837380, 2022).
Hepatic steatosis (continued). "As a regulator of mitochondrial β-oxidation, it is clear that altered PPARα activity is an important factor in the pathogenesis of alcohol-associated fatty liver, although it is equally clear that PPARα deficiency exacerbates ALD through multiple mechanisms in addition to impaired FA disposal." (PMID 35864895, 2022). "Likewise, systemic loss of PPARα coupled with a trans fatty acid-rich diet leads to hepatic steatosis." (PMID 36148775, 2022). "As hepatic fatty acid oxidation is central to systemic energy balance and liver steatosis susceptibility (associated with peroxisome proliferator-activated receptor alpha (PPARa) dysfunction), we analyzed the mRNA levels of ppara and the fatty acid oxidation-related PPARa target genes." (PMID 33919415, 2021). "Liver PPARα expression has been implicated as crucial in the development of hepatic steatosis." (PMID 32936538, 2020). "PRKAA1 and LIPE in Ethiopian humans and PPARA in Tibetan humans are both associated with lipid metabolism, which can be negatively impacted by chronic hypoxia as it increases the risk of developing fatty liver disease." (PMID 31154977, 2019). "Also, high-fat diet-induced hepatic steatosis in obese mice were associated with inhibited PPARα activity and increased expressions of SREBP-1c, as well as its target genes, FAS and SCD-1." (PMID 30398974, 2018). "We also show that CBD attenuates alcohol-induced liver steatosis and dysregulation of numerous key genes of fatty acid biosynthetic and oxidation pathways, mitochondrial pathways, and transcription factor PPARα, implicated in development of alcohol-induced steatohepatitis." (PMID 28935932, 2017). "Interestingly, defective PPARα signaling has been reported to cause hepatic mitochondrial and ER stress in the pathogenesis of hepatic steatosis through reduced mRNA expression of the sarco/endoplasmic reticulum calcium ATPase (SERCA)." (PMID 27367842, 2016). "Hepatocyte PPARα has been shown to play a major role in this adaptation, as PPARα-deficient mice are hypoglycaemic and exhibit impaired fatty acid oxidation that promotes hepatic steatosis during fasting." (PMID 27669233, 2016). "Additionally, 6-gingerol had a repressive effect on hepatic steatosis, which was associated with inducing PPARα expression." (PMID 25658238, 2015). "Finally, it is possible that worsening of hepatic steatosis with pioglitazone treatment in obese KKAy mice is a species-specific manifestation, similar to the hepatomegaly caused by PPARα agonists in rodents." (PMID 24799887, 2014). "Based on these findings, we tested the hypothesis that palmitoleic acid attenuates obesity-associated hepatic steatosis and inflammation by activating the nuclear receptor PPARα." (PMID 25147439, 2014). "Accordingly, Pparα-deficient mice develop hepatic steatosis on a high-fat diet." (PMID 23346097, 2013). "Taken together, these results suggest that the effect of zerumbone on the treatment of hepatic steatosis may be partly associated with the enhancement of gene expression involved in lipid metabolism through PPARα activation." (PMID 24223615, 2013). "Mice deficient in PPARα develop hepatic steatosis when fasted or fed a high-fat diet." (PMID 22675337, 2012). "Thus, the RAGE/PPARα regulator axis may be a therapeutic target for fatty liver disease associated with senescence." (PMID 37680899, 2023). "Since increased hepatic PPARγ2 leads to the development of fatty liver, the higher expression of Pparγ2 in the liver of male PPARα−/− mice, which show the compensatory expression of PPARγ, is associated with an increase in the liver TG level of male PPARα−/− mice, as previously reported." (PMID 36140300, 2022). "Moreover, liver steatosis susceptibility has been associated with PPARa dysfunction." (PMID 33919415, 2021).
Hepatic steatosis (continued). "Moreover, hesperidin prevented hepatic steatosis in western diet-fed rats by preventing the upregulation of lipogenesis-related genes Srebf1, and Scd1 caused by Western diet and the downregulation of Pparα and Cpt1a expression and CPT1a protein levels." (PMID 32785059, 2020). "The second possible molecular mechanism underlying CAV1-regulated hepatic steatosis might lie in the inhibition of PPARα, which is essential in the modulation of lipid metabolism as it activates the mitochondrial and peroxisomal fatty acid β-oxidation pathways." (PMID 28570612, 2017). "Saroglitazar, a dual PPARα/γ agonist, has shown potential in addressing liver steatosis, fibrosis, and dyslipidemia." (PMID 41450117, 2026). "MiR-21 promotes hepatic steatosis and fibrosis by targeting peroxisome proliferator-activated receptor alpha (PPARα) and activating hepatic stellate cells (HSCs)." (PMID 40141039, 2025). "In MAFLD, PPARα suppresses hepatic steatosis by upregulating genes involved in β-oxidation (CPT1A, carnitine palmitoyltransferase 1A; ACOX1, acyl-CoA oxidase 1) and inhibiting de novo lipogenesis (DNL)." (PMID 40564141, 2025). "Pharmacological Pparα agonists, such as WY-14,643 and pemafibrate, can reverse alcoholic fatty liver and improve liver function in mice and rats." (PMID 41465598, 2025). "miR-21 can target phosphatase and tensin homolog, which are involved in hepatic steatosis prevention, and PPARα expression, which activates lipid oxidation and determines inflammation and fibrosis progression in NAFLD." (PMID 41226441, 2025). "Both in vitro and in vivo, fEVs from HLF or PPARα suppression improved gut permeability and alleviated hepatic steatosis." (PMID 40236774, 2025). "Fibrates, which are PPARα agonists, such as fenofibrate, have been widely used to treat hyperlipidemia and have also been shown to reduce hepatic steatosis and MASLD." (PMID 40985048, 2025). "Conversely, strategies that upregulate PPARα or inhibit SREBP1c activity have been shown to alleviate hepatic steatosis and liver damage in obese and diabetic models." (PMID 40869259, 2025). "The toxicodynamic interaction between DIF and MDP in promoting liver steatosis is evidenced by the combined downregulation of both PPARA and ACOX1, along with increased triglyceride accumulation." (PMID 40295322, 2025). "Escherichia_Shigella can induce hepatic steatosis, ballooning, hepatic inflammation and fibrosis by inhibiting the expression of hepatic peroxisome proliferator activated receptor PPARα." (PMID 40607347, 2025). "In the present study, we suspected that the AMPK/mTOR and PPARα pathways are involved in L-Phe-induced liver steatosis." (PMID 40588730, 2025). "For instance, IRF9 has been reported to promote the transcription of Pparα, improving hepatic steatosis or inhibiting SIRT1 activity, thus mitigating liver ischemic injury." (PMID 40083324, 2025). "The activation of PPARα plays a central role in regulating lipid metabolism and reducing triglyceride accumulation in the liver, thus contributing to the prevention of hepatic steatosis and conditions such as MASLD and hyperlipidemia." (PMID 40926269, 2025). "Enhancing PPARα activity or inhibiting SREBP1c are effective strategies to mitigate liver steatosis and damage in obese and diabetic animals." (PMID 40689212, 2025). "Statins also alter PPARs, particularly PPARα, which improves fatty acid metabolism and decreases fibrosis, IR, and liver steatosis." (PMID 40244398, 2025). "Mechanistically, C18:1n9c activates PPARα, promotes lipolysis and ameliorates hepatic steatosis in Angus bulls." (PMID 41373709, 2025). "The activation of PPARα, both individually and in conjunction with FGF15 overexpression, led to weight loss and reduced liver steatosis." (PMID 40815899, 2025).
Hepatic steatosis (continued). "Peroxisome proliferator-activated receptor α (PPARα) or Kruppel-like factor 15 (KLF15) can also ameliorate hepatic steatosis through inhibition of SREBP-1c activation to reduce the synthesis of fatty acids and triacylglycerols." (PMID 39911797, 2025). "Systemic or liver-specific knockout of PPARα aggravates hepatic steatosis and obesity induced by HFD or MASH diet in mice." (PMID 39911797, 2025). "Hepatic expression of PPARα is negatively correlated with the prevalence of liver steatosis and MASH." (PMID 40985048, 2025). "These improvements in hepatic steatosis are consistent with the mechanism of PPARα activation, which enhances β-oxidation of fatty acids and reduces hepatic triglyceride accumulation." (PMID 41583325, 2025). "The importance of PPARα in this process is further demonstrated by studies on Pparα-null (Pparα−/−) mice, which show profound metabolic abnormalities when fasted, including hepatic steatosis, hypoglycemia, and hypoketonemia." (PMID 40565288, 2025). "Conversely, defects in Pparα-inducible fatty acid oxidation result in more severe hepatic steatosis during fasting, attributed to dysfunctional peroxisomal β-oxidation and loss of Acox1 activity." (PMID 41465598, 2025). "Supplementation of VD3 alleviated liver steatosis in high-fat-induced obese mice and mitigated hepatic steatosis by regulating fatty acid uptake and β-oxidation through PPARα signaling pathway in mice." (PMID 39981311, 2025). "Activation of PPARα using fibrate medications (clofibrate and fenofibrate) to treat fatty liver is performed in clinical intervention trials." (PMID 39911797, 2025). "In support of this, several studies have reported that either CSAD-LOE or taurine administration up-regulated PPARα and alleviated hepatic steatosis in various animal models with fatty liver." (PMID 40577472, 2025). "CPT1α, another rate‐limiting enzyme in fatty acid β‐oxidation regulated by PPARα, has also been demonstrated to reduce hepatic steatosis in mice when its activity is enhanced." (PMID 41362700, 2025). "Preclinical models demonstrated that PE-CSLT modulates AMPK/SREBP1/ACACA/PPARa signaling to attenuate hepatic steatosis and dyslipidemia, providing mechanistic support for its therapeutic potential." (PMID 40708046, 2025). "In response to endoplasmic reticulum stress, activating transcription factor 6α (ATF6α) can attenuate liver steatosis by stimulating PPARα-mediated FAO." (PMID 39911797, 2025). "Taken together, these results suggest that FABP5‐asprosin interaction promotes hepatic steatosis, inflammation, and fibrosis progression by inhibiting PPARα activity in mice." (PMID 40231957, 2025). "The central role of PPARα in orchestrating ketogenesis has been conclusively demonstrated in PPARα-knockout mice, which exhibit severely impaired ketogenic capacity and develop hepatic steatosis when challenged with fasting or high-fat diets." (PMID 41463929, 2025). "The use of PPARα agonists has been shown to attenuate hepatic steatosis, ballooning, and inflammatory markers in MASLD mouse models." (PMID 41362700, 2025). "Saroglitazar, a PPARα/γ dual agonist, significantly reduced alanine aminotransferase levels, insulin resistance, dyslipidemia, hepatic steatosis, and fibrosis markers in MASLD patients during phase II trials (4 mg dose)." (PMID 41362700, 2025). "As a master regulator of fatty acid catabolism in the liver, PPARα agonist treatment protects mice from diet-induced fatty liver diseases." (PMID 40981382, 2025). "Chronic liver diseases, including liver steatosis and fibrosis, are driven in part by dysregulation of PPARα and lipid metabolism." (PMID 40793786, 2025). "Pparα agonists have also been reported to inhibit Srebf1 expression and Pparα activation reduces the development of hepatic steatosis." (PMID 39537943, 2024).
Hepatic steatosis (continued). "Rab30 is highly induced in the liver of Cpt2L−/− mice that cannot perform hepatic β-oxidation and therefore exhibit fasting-induced hepatic steatosis, serum dyslipidemia, and increased Pparα transcriptional activity." (PMID 38796472, 2024). "A PPARα agonist can ameliorate mitochondrial dysfunction and inhibit hepatic steatosis in MASLD mice." (PMID 39334795, 2024). "PPARα has proven effects in reducing body weight, serum lipids, and fasting glucose levels, improving insulin sensitivity, and preventing hepatic steatosis and NAFLD in animal models." (PMID 39202687, 2024). "A reduction in PPARα expression was observed in individuals with hepatic steatosis, and a PPARα agonist was used to ameliorate this symptom." (PMID 39458470, 2024). "When Lactobacillus kefiri DH5 treatment was given to HFD-fed mice, hepatic steatosis was significantly higher in the control group, while PPARα expression was significantly upregulated in the adipose tissue of the Lactobacillus-treated group." (PMID 39451206, 2024). "Histological analyses confirmed that hepatic Pparα overexpression significantly ameliorated hepatic steatosis in these mice." (PMID 39395794, 2024). "Pathway analysis showed enrichment of genes related PPARα activation and unfolded protein response, and further confirmed enhanced hepatic fibrosis and liver steatosis." (PMID 39372760, 2024). "Schisandra sphenanthera improves liver steatosis and inflammation via activating PPARα/γ signaling in C57BL/6J mice with NAFLD." (PMID 38699583, 2024). "In pig sepsis, PPARα decline has been shown to precede hepatic steatosis, mirroring findings in CLP mice." (PMID 39261648, 2024). "These circRNAs act as endogenous regulators of miR‐34a, reducing hepatic steatosis by suppressing the interaction of miR‐34a with MRE within PPARα mRNA." (PMID 39239069, 2024). "Aberrant circRNA_0046366 and circRNA_0046367/miR‐34a/PPARα signaling is the potential novel target for treating hepatic steatosis." (PMID 39239069, 2024). "EPA has been shown to have beneficial effects in HFD-induced liver steatosis and decline in energy metabolism, possibly through its interaction with PPARα." (PMID 38515850, 2024). "Peroxisome proliferator-activated receptor γ coactivator-1α (PGC-1α), AMP-activated protein kinase (AMPK), and peroxisome proliferator-activated receptor α (PPARα) activation play roles in suppressing hepatic steatosis through multiple pathways." (PMID 38532480, 2024). "IRF9 interacted with peroxisome proliferator-activated receptor α (PPARα) and activated PPARα target genes to attenuate inflammation, hepatic steatosis, and insulin resistance." (PMID 38999981, 2024). "In this context, AMPK, Sirt1, SREBP1c, and PPARα signaling pathways have been highlighted as major molecular targets for novel therapeutic agents aimed at inhibiting the progression of hepatic steatosis." (PMID 39334796, 2024). "miR‐34a can bind to PPARα in rodents, which suppresses lipid metabolism and enhances hepatic steatosis, while circRNA_0046366 and circRNA_0046367 compete against PPARα for binding to miR‐34a." (PMID 39239069, 2024). "The alleviation of fatty liver by atorvastatin, a lipid-regulating drug, has been demonstrated to be due to an increase in hepatic PPARα expression in rats." (PMID 39458470, 2024). "In a recent study, a newly discovered phytocannabinoid (E)-β-caryophyllene was found to counteract the reduction of PPARα in hepatic steatosis." (PMID 38397045, 2024). "As a key regulator of liver metabolism, Peroxisome Proliferator Activated Receptor Alpha (PPARα) was activated in rodent models, thereby improving hepatic steatosis, inflammation, and fibrosis." (PMID 39409181, 2024). "On the one hand, vitamin K supplementation is known to attenuate fat diet-induced hepatic steatosis by regulating the AMPK/SREBP1/PPARα signaling pathways via the activation of GAS6." (PMID 39404394, 2024).